Y_RNA (Y RNA )
Gene: Miscellaneous RNA gene on chromosome 2 (86,159,956 to 86,160,066, reverse strand). Ensembl gene ENSG00000200241.
Homologues: Orthologues: chimpanzee Y_RNA (98% identical), macaque Y_RNA (93% identical), guinea pig Y_RNA (68% identical). Paralogues in human: RNY1 (86% identical), Y_RNA (85% identical), Y_RNA (83% identical), Y_RNA (82% identical), RNY1P11 (81% identical), Y_RNA (81% identical), Y_RNA (80% identical), RNY1P8 (79% identical), Y_RNA (79% identical), RNY1P7 (78% identical), Y_RNA (78% identical), Y_RNA (77% identical), and 95 more.